CXCL11 (C-X-C motif chemokine ligand 11)
Diseases named in the same sentence as CXCL11 in open-access papers (continued):
Sharing a sentence is not in itself a finding about the gene and the disease.
pneumonia (2 papers, 2017 to 2021). An acute, acute and chronic, or chronic inflammation focally or diffusely affecting the lung parenchyma, caused by an infection in one or both of the lungs (by bacteria, viruses, fungi, or mycoplasma.). "In an independent set of samples assayed using RT-qPCR, Ifnar2 and the interferon-responsive genes Cxcl11, Ifit1, Irf5 and Isg15 were confirmed to be upregulated during pneumonia." (PMID 28900269, 2017). "Interestingly, in the interferon signaling pathways, Ifnar2 and the interferon-responsive genes Cxcl11, Ifit1, Irf5 and Isg15 were verified to be upregulated during pneumonia, documenting that neutrophils are well able to respond to type I interferon signaling." (PMID 28900269, 2017).
polymyositis (2 papers, 2014 to 2023). A rare idiopathic inflammatory myopathy characterized by symmetric proximal muscle weakness and elevated muscle enzymes. "Enriched genes including CXCL11 and CD244 are considered potential biomarkers for polymyositis." (PMID 38137330, 2023). "However, we chose CXCL10 in this study because its expression is abundant in the muscle tissue of CIM in this study and polymyositis unlike CXCL9 or CXCL11." (PMID 24939012, 2014). "In previous reports on IIMs, CXCL10 was abundantly expressed on macrophages and T cells in polymyositis, inclusion body myositis and dermatomyositis whereas CXCL9 and CXCL11 were not altered compared to the control." (PMID 24939012, 2014).
preeclampsia (2 papers, 2023 to 2025). Preeclampsia is a hypertensive disorder of pregnancy that is characterized by new-onset hypertension with proteinuria presenting after 20 weeks of gestation, and depending on mild or severe forms may initially present with severe headache, visual disturbances, and hyperreflexia. "Studies have shown that miR-101 plays a role in the formation of preeclampsia by reducing the expression of BRD4 protein, resulting in the inhibition of the NF-κB/CXCL11 signaling pathway and ultimately enhancing the proliferation and movement capabilities of placental trophoblast cells." (PMID 40104134, 2025).
pulmonary sarcoidosis (2 papers, 2016 to 2023). Sarcoidosis affecting the lung parenchyma. "CXCL11 and CXCL10 may play a role in the accumulation of Th1 cells in pulmonary sarcoidosis, a Th1-associated disease." (PMID 27776524, 2016). "CXCR3 ligands, CXCL9 and CXCL11, are augmented in BALF from pulmonary sarcoidosis." (PMID 36949950, 2023).
pulmonary tuberculosis (2 papers, 2012 to 2023). A bacterial infection that affects the lungs and is caused by Mycobacterium tuberculosis. "Moreover, the levels of IP-10, CXCL11 and CXCL12 expression in LTB2 plasma were not significantly different from the levels found in pulmonary tuberculosis patients but were much higher than the levels detected in the healthy control group." (PMID 23028695, 2012).
Q fever (2 papers, 2017 to 2018). A bacterial infection caused by Coxiella burnetii. "One limitation is the small group size of QFS patients who recovered from their complaints and missing CXCL9, CXCL10, and CXCL11 data for asymptomatic Q fever seropositive controls." (PMID 29804281, 2018). "Unfortunately, we were unable to test antigen-specific CXCL9, CXCL10, and CXCL11 production in asymptomatic Q fever seropositive controls." (PMID 29804281, 2018). "A Receiver-operator-curve (ROC) analysis was performed for CXCL9 and CXCL11 to distinguish between chronic Q fever patients and past Q fever patients." (PMID 28793883, 2017). "CXCL11 production in chronic Q fever patients (median 146 pg/mL, IQR 83–230) was higher than in past Q fever patients (median 66 pg/mL, IQR 43–183, p < 0.05)." (PMID 28793883, 2017). "Additionally, due to an interassay coefficient of variability well above 15%, we had to exclude data for antigen-specific CXCL9, CXCL10, and CXCL11 production in asymptomatic Q fever seropositive controls." (PMID 29804281, 2018). "Furthermore, a recent study has shown a promising role for chemokines CXCL9, CXCL10, and CXCL11 as potential new biomarkers for persistent infection with C. burnetii, i.e. chronic Q fever." (PMID 29804281, 2018). "However, CXCL9 and CXCL11 production was significantly higher for chronic Q fever patients compared to past Q fever individuals." (PMID 28793883, 2017). "Gene expression of the chemokines CXCL9, CXCL10, CXCL11 and CCL8 was strongly up-regulated in C. burnetii stimulated PBMCs of chronic Q fever patients, in contrast to healthy controls." (PMID 28793883, 2017). "Chronic Q fever patients showed increased production of all four chemokines (CXCL9, CXCL10, CXCL11 and CCL8)." (PMID 28793883, 2017). "Chronic Q fever patients did not have higher levels of CXCL10 or CXCL11 than past Q fever individuals (median 204 pg/mL,10–464 and median 18 pg/mL, 6–72)." (PMID 28793883, 2017). "C. burnetii-specific IFNy, IL-2, CXCL9, CXCL10, and CXCL11 production were tested in ex vivo stimulated whole blood of QFS patients who recovered from their complaints (n = 8), QFS patients with persisting complaints (n = 27), and asymptomatic Q fever seropositive controls (n = 10)." (PMID 29804281, 2018). "A recent study showed that antigen-specific production of CXCL9 and CXCL11, but not CXCL10, could further help differentiate chronic Q fever patients from Q fever seropositive controls." (PMID 29804281, 2018).
rectal adenocarcinoma (2 papers, 2021 to 2023). "We determined the distribution of CXCL11 in tumor tissue across all TCGA cancers and found that CXCL11 expression was significantly upregulated in both COAD and rectal adenocarcinoma (READ)." (PMID 33777950, 2021).
rosacea (2 papers, 2022 to 2025). A chronic erythematous skin disorder that affects the face. "Furthermore, CXCL11 levels and T-cell surface glycoprotein CD6 isoform levels are risk factors for rosacea, while MCP-1 levels and PD-L1 levels are protective factors for rosacea." (PMID 41431076, 2025).
Rotavirus infection (2 papers, 2017 to 2021). Infection with any of the rotaviruses. "Of interest, several IFN inducible genes (OAS1, MX1, IL18, IITP3, TAP1, and RSAD2) as well as several cytokines and chemokines (CCL5, CXCL10, CXCL11, IL8, and CCL15) were upregulated by rotavirus infection." (PMID 28210256, 2017). "These partially shared DEGs included for example C-X-C Motif Chemokine Ligand 11 (CXCL11) and Bone Marrow Stromal Cell Antigen 2 (BST2, also called Tetherin), which was up-regulated in response to norovirus and astrovirus but not rotavirus infection." (PMID 34205050, 2021).
scleroderma (2 papers, 2021 to 2023). Scleroderma is a rare autoimmune connective tissue disorder characterized by abnormal hardening of the skin and, sometimes, other organs. "A study indicates that enriched genes including MPO (myeloperoxidase), RXFP1, CXCL11, CTNND2, BMPR2, TLR3, CCR2, and CAV1 are altered expressed in scleroderma." (PMID 38137330, 2023).
squamous cell carcinoma (2 papers, 2022 to 2023). A carcinoma arising from squamous epithelial cells. "To investigate the anti-tumor effects of the IFN-inducible chemokines CXCL9, CXCL10, and CXCL11, we generated a cell line stably expressing these IFN-inducible chemokines using the mouse squamous cell carcinoma cell line SCCVII." (PMID 37218983, 2023).
viral hepatitis (2 papers, 2017 to 2023). An acute or chronic inflammation of the liver parenchyma caused by viruses. "CXCL11 was described as a marker of liver injury caused by viral hepatitis and was even positively associated with development of HCC compared to non-cirrhotic controls in patients with chronic HCV and HBV infection." (PMID 36982370, 2023).
acute GVHD (1 paper, 2024). "Specifically, the upregulation of CXCL9, CXCL10, and CXCL11 in the skin of patients with acute GVHD promotes the recruitment of eosinophils and T cells to the sites of injury." (PMID 39840040, 2024).
Acute hepatitis (1 paper, 2022). Acute hepatic injury resulting from inflammation typically accompanied by increased serum alanine transaminase activity. "Similar results have only been found in one acute hepatitis study, where CXCL9, CXCL10, CXCL11 and CXCL13 elevated during the acute phase but then decreased in conjunction with an HBsAg decline." (PMID 36304473, 2022).
anthrax (1 paper, 2010). "Combinatorial neutralization of CXCL9 together with CXCL10 or CXCL10/CXCL11 during pulmonary B. anthracis infection significantly increased host susceptibility to anthrax, with neutralization of all three CXC chemokines resulting in 50% mortality (p = 0.0003)." (PMID 21124994, 2010). "To gain insight into disease progression associated with the neutralization of CXCL9, CXCL10, and CXCL11, and to confirm that host death resulted as a consequence of B. anthracis infection, we investigated two salient features of anthrax: bacterial dissemination and toxemia." (PMID 21124994, 2010). "As the induction of the interferon-inducible ELR- CXC chemokines within the lungs of spore-challenged mice is associated with resistance to inhalational anthrax, we sought to determine whether murine CXCL9, CXCL10, and CXCL11 exert antimicrobial activity against B. anthracis Sterne strain." (PMID 21124994, 2010).
Anxiety (1 paper, 2021). Intense feelings of nervousness, tension, or panic often arise in response to interpersonal stresses. "Positive correlations were observed between MIP-1α/CCL3, MIP-1β/CCL4, MCP-1/CCL2, MIP-3α/CCL20, RANTES/CCL5, Eotaxin/CCL11, and I-TAC/CXCL11 with high scores for anxiety (HARS) (p < 0.05) and for depression (HDRS) (p < 0.004)." (PMID 34863117, 2021).
aseptic aseptic meningitis (1 paper, 2023). "The study on aseptic meningitis caused by nonpoliomyelitis enterovirus infection in children showed that the levels of CXCL10 and CXCL11 in CSF were higher than those in normal children, and CXCL10 levels may have high differential value to identify nonpolio aseptic aseptic meningitis." (PMID 37904697, 2023).
Atherosclerotic lesion (1 paper, 2015). A lesion associated with atherosclerosis, a multifactorial and multipart progressive disease manifested by the focal development within the arterial wall of lesions, that ranges from the development of a fatty streak, plaque progression, and plaque disruption. "CXCR3 receptor is activated by IFN-γ-inducible chemokines such as CXCL9, CXCL10 (IP-10), and CXCL11 (I-TAC), which are highly expressed in atherosclerotic lesions and play an important role in Th1-cell homing." (PMID 25873769, 2015).
B cell deficiency (1 paper, 2016). A broad classification of disorders where circulating numbers of B lymphocytes are decreased or ineffective. "We found decreased expression of RANTES, MCP-5, IP-10, CXCL11, and TNF following B cell deficiency or depletion in MRL/lpr mice." (PMID 27055816, 2016).
bacterial pneumonia (1 paper, 2025). Acute infection of the lung parenchyma caused by bacteria (e.g., Streptococcus pneumoniae, Haemophilus influenzae, Chlamydia pneumoniae, Mycoplasma pneumoniae, and Legionella pneumophila). "The CCL18, CXCL9, CXCL10, CXCL11, and MMP9 levels were also elevated in patients with other respiratory diseases, such as bacterial pneumonia and COPD." (PMID 40269953, 2025).
Candidemia (1 paper, 2025). A form of invasive candidiasis where species of CANDIDA are present in the blood. "The proteomic profile in candidemia included eight of the most significantly upregulated DEPs: CXCL11, LAP-TGF beta-1, CD40, CXCL1, CXCL6, IL18, CXCL10, and uPA." (PMID 41229429, 2025). "The highest upregulated expressions in isolated candidemia included CXCL6, LAP-TGF beta-1, CXCL1, CXCL11, and CD5, while in candidemia with bacterial co-infection, CXCL11, CD40, uPA, CXCL1, CXCL10, and IL-18 were the most abundantly upregulated." (PMID 41229429, 2025).
Cerebral ischemia (1 paper, 2013). Restriction of arterial blood supply to the brain associated with insufficient oxygenation to support the metabolic requirements of the tissue. "Only chemokine ligand-9 (CXCL9), chemokine ligand-11 (CXCL11), and chemokine receptor-1 (XCR1) have not been, to our knowledge, previously examined with their relations to cerebral ischemia." (PMID 24244400, 2013).
cerebral toxoplasmosis (1 paper, 2018). Infections of the brain caused by the protozoan toxoplasma gondii that primarily arise in individuals with immunologic deficiency syndromes (see also aids-related opportunistic infections). "In murine ocular and cerebral toxoplasmosis, there is a significant increase in the expression levels of CXCL10 and CXCL11 over the course of infection." (PMID 29459857, 2018).
cervical tumor (1 paper, 2022). "To investigate whether EphA2 can also regulate the expression of CXCL11 and PD-L1 in vivo, we established the xenograft cervical tumor model." (PMID 36478746, 2022).
chlamydial infection (1 paper, 2020). "CXCL11 can induce and recruit CXCR3+ T cells shown to be protective during chlamydial infection, and could therefore prevent ascension." (PMID 32127796, 2020).
chordoma (1 paper, 2025). Chordomas are rare malignant tumors arising from embryonic remnants of the notochord in axial skeleton. "The expression analysis identified significant downregulation of SPOCK3, NRK, MYH8, DLK1 and SLN, alongside upregulation of HLA-DQA1, GDA, CXCL11, CXCL9 and ADAMDEC1 in chordomas." (PMID 40386066, 2025).
chorioamnionitis (1 paper, 2014). A morphologic finding indicating inflammation of the fetal sac membranes. "As an example, in the chorioamnionitis, placental inflammatory lesions parallel an increase in CXCL10, CXCL11 and CXCL12 concentrations in maternal plasma." (PMID 24849800, 2014).
chronic hepatitis (1 paper, 2024). An active inflammatory process affecting the liver for more than six months. "The slopes of CXCL9, CXCL10, CXCL11, and TIGIT were higher in T cells of chronic hepatitis patients than in those of patients with HBeAg+ chronic infection and HBeAg− chronic infection, indicating that the expression of these genes was increased in the corresponding cell types." (PMID 39135698, 2024).
colorectal tumors (1 paper, 2019). "Specifically, cytokines that were previously shown to correlate with the cytolytic index (C1QA, C1QB, C1QC, CXCL9, CXCL10, CXCL11 and CXCL13), were upregulated in CYT-high colorectal tumors." (PMID 31429779, 2019).
Cough (1 paper, 2017). A sudden, audible expulsion of air from the lungs through a partially closed glottis, preceded by inhalation. "Poly(I:C), as expected, up-regulated genes associated with inflammation, innate immunity and viral responses including CXCL11, CCL5 (chemokine (C–C motif) ligand) 5 and CXCL10, interferon-induced protein 44 like (IFI44L) in ASMCs from both healthy non-cough and chronic cough volunteers." (PMID 28842514, 2017).
cutaneous leishmaniasis (1 paper, 2023). Leishmaniasis affecting the skin. "CXCL11 also promotes susceptibility to cutaneous leishmaniasis in mice by promoting Th2 and inhibiting Th1 responses." (PMID 38250073, 2023).
cutaneous melanoma (1 paper, 2020). A primary melanoma arising from atypical melanocytes in the skin. "In addition, compared with the normal control, the expression of IGHV1-18, CXCL11 and HLA-DQB1 were higher in the patients with cutaneous melanoma, while the expression of LTF was lower." (PMID 33585219, 2020). "We found that the expression of CXCL11 (P = 0.1), LTF (P = 0.28), and HLA-DQB1 (P = 0.67) had no significant relation to the subtypes of cutaneous melanoma through TISIDB database." (PMID 33585219, 2020).
cutaneous T-cell lymphoma (1 paper, 2023). "Work from our collaborators demonstrated that GaM decreased the expression of pro-angiogenic cytokine IL-10 in a mouse model of cutaneous T-cell lymphoma, whereas angiostatic proteins CXCL10 and CXCL11 were significantly upregulated." (PMID 38288102, 2023).
dementia (1 paper, 2023). Loss of intellectual abilities interfering with an individual's social and occupational functions. "Increased expression of CXCL9 to CXCL11 is typically induced by antiviral or IFN-associated signaling, which regulates glial functions and is linked to cognitive changes, dementia, and neuropsychiatric disorders." (PMID 37075107, 2023).
diabetic neuropathy (1 paper, 2015). A chronic, pathological complication associated with diabetes mellitus, where nerve damages are incurred due to diabetic microvascular injury involving small blood vessels that supply these nerves, resulting in peripheral and/or autonomic nerve dysfunction. "This study verifies that, in streptozotocin-induced diabetic neuropathy, the spinal protein levels of CXCL1, CXCL5, CXCL9, and CXCL12, but not CXCL11 and CXCL13, are upregulated." (PMID 25789329, 2015). "Our results suggest that, at day 7, CXCL11 and CXCL13 are not involved in STZ-induced diabetic neuropathy." (PMID 25789329, 2015).
diffuse large B-cell lymphoma (1 paper, 2016). "The T cell-attracting chemokine chemokine (C-X-C motif) ligand 11 (CXCL-11) was found to be a target of miR-BHRF1-3 in the type III latency cell line Burkitt lymphoma-5R (BL-5R) and diffuse large B cell lymphoma (DLBCL)." (PMID 27070595, 2016).
dilated cardiomyopathy (1 paper, 2022). Cardiomyopathy which is characterized by dilation and contractile dysfunction of the left and right ventricles. "While CXCL9, CXCL10, and CXCL11 belong to the chemokine family, CX3CR1, ADORA3 and SAA1 have not been reported in dilated cardiomyopathy, and further research is needed." (PMID 35618744, 2022).
dry eye (1 paper, 2024). "Here, we evaluated the expression of the C-C motif chemokine CCL3 and CXC motif chemokine ligand CXCL11 in our dry eye model." (PMID 38399289, 2024).
Ebola (1 paper, 2016). "We also found several cytokines, such as CCL7 and CXCL11 (I-TAC), that showed significant changes in expression but whose protein levels have not been previously observed during Ebola pathogenesis." (PMID 27595844, 2016).
eczema (1 paper, 2017). "In skin lesions from eczema, the mean percentages of inflammatory cells expressing CXCL9, CXCL10, CXCL11 and CXCR3 were 4.8% ± 5.8%, 5.2% ± 6.3%, 63.2% ± 15.7% and 25.2% ± 13.0%, respectively." (PMID 28436448, 2017).
endotoxemia (1 paper, 2019). "Similarly, glucocorticoids have been shown to inhibit Cxcl11 upregulation in fluticasone propionate-stimulated peripheral blood monocytes, and in IFN-γ- or LPS-stimulated RAW 264.7 macrophages, as well as in multiple tissues of endotoxemia mice." (PMID 31072958, 2019).
esophagitis (1 paper, 2026). An acute or chronic inflammatory disease affecting the esophageal wall. "In contrast, EoE-like esophagitis was primarily immune-driven, marked by CXCR3 ligand activation (CXCL9, CXCL10, CXCL11) and immunoglobulin complex enrichment, indicating systemic immune dysregulation and a potential precursor state to conventional EoE." (PMID 41818315, 2026).
Flavivirus Infections (1 paper, 2025). Infections with viruses of the genus FLAVIVIRUS, family FLAVIVIRIDAE. "CXCL10 and CXCL11 are chemokine markers of the IFN-I response, and they are induced by IFN during flavivirus infections." (PMID 40431659, 2025).
gastric adenocarcinoma (1 paper, 2019). "Previous research had reported that CXCL13 is associated with CRC infiltration by distinct T cell subsets, and CXCL11 is a member of the confirmed prognostic model of gastric adenocarcinoma." (PMID 31689990, 2019).
geographic atrophy (1 paper, 2016). "Up-regulation of Ccl2, Cxcl1, Cxcl10, and Cxcl11 are present in all forms of AMD, and the Ccl2/Ccr2 axis is implicated in the pathogenic accumulation of macrophages to the outer retina in models that feature aspects of either CNV or geographic atrophy, such as light damage." (PMID 26911327, 2016).
germinoma (1 paper, 2010). A malignant germ cell tumor arising in the central nervous system. "Six genes (BANK1, CXCL9, CXCL11, DDIT4L, ELOVL6 and HERC5) within 4q13.3-4q28.3 were more abundant in germinomas." (PMID 20178649, 2010).